PROM1 (prominin 1)
Diseases named in the same sentence as PROM1 in open-access papers (continued):
Sharing a sentence is not in itself a finding about the gene and the disease.
retinal degeneration (continued). "Besides being a marker of various somatic stem cells in mammals, prominin-1 (CD133) plays a role in maintaining the photoreceptor integrity since mutations in the PROM1 gene are linked with retinal degeneration." (PMID 21407811, 2011). "Furthermore, ultra-widefield imaging, especially FAF and FFA, may be beneficial for the detection of mild peripheral degenerative changes in retinal degeneration caused by the PROM1 p.R373C variant." (PMID 38072963, 2023). "Increased mTORC1 signaling and impaired RPE cell autophagy contribute to other forms of retinal degeneration, including age-related macular degeneration (AMD), Stargardt Disease, and PROM1-associated macular dystrophy." (PMID 38920696, 2024). "This phenotype is consistent with the autosomal recessive slow progressive retinal degeneration seen in human PROM1-null patients, who can take 15–50 years to develop a severe clinical phenotype." (PMID 39355864, 2024). "In conclusion, the autosomal dominant variant PROM1 p.R373C constitutes a significant proportion of PROM1-related retinal degeneration cases in the Korean population." (PMID 38072963, 2023). "In conclusion, the autosomal dominant variant PROM1 p.R373C accounts for a significant proportion of all PROM1-related retinal degeneration cases in the Korean population." (PMID 38072963, 2023). "The genetic and clinical heterogeneity observed in PROM1-related retinal degeneration highlights the intricate role of the PROM1 gene in the pathomechanism of inherited retinal diseases (IRDs)." (PMID 38072963, 2023). "Determining the precise pathomechanism of PROM1-related retinal degeneration is vital for the future development and implementation of potential therapeutic options, such as gene therapy." (PMID 38072963, 2023). "We next attempted to capture the primary events at the onset of retinal degeneration in Prom1-KO mice." (PMID 34664634, 2021). "We have here described early manifestations of the retinal degeneration that occurs in Prom1-KO mice and identified genes related to this process." (PMID 34664634, 2021). "Our results suggested that a critical point for retinal degeneration in Prom1-KO mice exists between P14 and P21." (PMID 34664634, 2021). "Prom1-knockout (KO) mice recapitulate key features of these diseases including light-dependent retinal degeneration and constriction of retinal blood vessels." (PMID 34664634, 2021). "To characterize the role of Prom1 dysfunction in retinal degeneration and thereby to provide insight into potential treatments for Prom1 mutation-associated RP and MD, we here investigated the initial manifestations of such degeneration." (PMID 34664634, 2021). "The aim of this study is to analyze the sequence variations in the PROM1 gene in a series of patients to understand better their potential for pathophysiological consequences on retinal degeneration." (PMID 31199449, 2019). "This case series characterizes the clinical phenotype and molecular genetic variations in patients with retinal degeneration and PROM1 sequence variations." (PMID 31199449, 2019). "Disruption of REP-1, PROM1, ELOVL4, or ABCA4, each involved in lipid processing, causes early-onset retinal degeneration." (PMID 29321376, 2018). "Although prominin-1 is broadly expressed, the principle phenotype observed in patients is retinal degeneration." (PMID 21655362, 2011). "The mice attenuated with the Prom1 gene (Prom1−/−; Prom1-KO) well recapitulate the symptoms found in human patients, making the Prom1-mutant mice a suitable animal model to investigate the progression of retinal degeneration." (PMID 38252153, 2024). "The implications of Prom1-KD causing aAMD-like RPE defects and retinal degeneration in a mouse model are significant and could lead to novel treatments for aAMD." (PMID 39513868, 2024).
retinal degeneration (continued). "Considering these findings, it is speculated that PROM1-related retinal degeneration may be influenced by interactions with other genes, epigenetic factors, or environmental influences, which could explain the observed phenotypic heterogeneity." (PMID 38072963, 2023). "However, the mechanisms by which Prom1 prevents retinal degeneration triggered by light stimulation have remained elusive." (PMID 34664634, 2021). "A better understanding of the clinical and molecular characteristics of PROM1-related retinal degeneration may aid development of future treatments, including gene therapy and optogenetics." (PMID 31199449, 2019). "What are the clinical and molecular characteristics of PROM1-related retinal degeneration?" (PMID 31199449, 2019). "Together, these findings indicated that retinal development remains intact in Prom1-KO mice until P14, after which an increase in the numbers of GFAP-positive glial cells and apoptotic photoreceptors occurs in association with eye opening and the onset of retinal degeneration." (PMID 34664634, 2021). "However, as the knowledge of the molecular characteristics and the signalling pathway(s) induced by Prom1 is still fragmented, the mechanisms by which the retinal degeneration initiates remain unclear." (PMID 31685837, 2019). "Given the elevated expression of Edn2 and Gfap apparent in the retina of Prom1-KO mice, we hypothesized that ET-2, the mature form of the Edn2 product, might induce the GFAP expression apparent in association with retinal degeneration in the Prom1-deficient animals." (PMID 34664634, 2021). "Animal models lacking Prom1 or expressing the dominant Arg373Cys mutant recapitulate the retinal degeneration phenotype and display defects in disk morphogenesis." (PMID 36215230, 2022). "Like prominin-1, musashi-1 appears indispensable for the maintenance of photoreceptors, and mice lacking it suffer from retinal degeneration mimicking retinitis pigmentosa." (PMID 21407811, 2011).
breast tumors (26 papers, 2007 to 2026). "Brain metastases as the first site of distant recurrence were associated most frequently with the basal subtype and primary tumor expression of nestin, prominin-1, or CK-5, and, on the other hand, they were rare when the breast tumor expressed ER or PgR." (PMID 21914172, 2011). "Interestingly, the almost totality of the data on breast tumors correlate CD133 with molecules involved in cell motility and invasion, suggesting a direct role of PROM1 in modulating the potential malignancy of breast tumors." (PMID 31636668, 2019).
cone-rod dystrophy (25 papers, 2009 to 2025). Inherited retinal dystrophies that belong to the group of pigmentary retinopathies. "Membrane bending activity is particularly evident in photoreceptors, where Prom1 loss-of-function mutations cause failure of outer segment homeostasis, leading to cone-rod retinal dystrophy (CRRD)." (PMID 37986829, 2024). "PROM1 is known to be expressed in RB cell lines and the adult retina and mutations are associated with cone-rod dystrophy, retinal macular dystrophy and retinitis pigmentosa." (PMID 39695086, 2024). "If the complexes prove to be PROM1 oligomers they can provide a possible path towards understanding the dominance of Prom1 mutations in patients with cone-rod dystrophy." (PMID 36215230, 2022). "Patients with the recurrent PROM1 mutation are known to have phenotypes ranging from isolated macular dystrophy, rod dystrophy, rod-cone dystrophy and cone-rod dystrophy." (PMID 28076437, 2017). "The variant list following analysis of patient 114 (a male) highlighted the heterozygous PROM1 mutation (c.1117C>T, p.R373C) which was previously identified in patients with a diagnosis of cone-rod dystrophy as the possible cause of disease symptoms." (PMID 25133751, 2014). "We describe a consanguineous Arab family who has a novel PROM1 mutation that functionally disrupts both types of photoreceptors and presents as cone-rod dystrophy." (PMID 19718270, 2009). "PROM1 encodes the protein promin-1, implicated in the morphological genesis of photoreceptor disks: pathogenic variants in promin-1 are, therefore, correlated with macular and cone-rod dystrophies, displaying both dominant and recessive modes of inheritance." (PMID 40426944, 2025). "In addition, PROM1 mutations were reported to cause cone-rod dystrophy with high myopia and nystagmus." (PMID 37449273, 2023). "Mutations in the human PROM1 gene have been reported in cases of Retinitis Pigmentosa, Stargardt Disease, Macular Dystrophy, Leber Congenital Amaurosis and are primarily associated with cone-rod dystrophy." (PMID 36215230, 2022). "Although previous genetic reports have described numerous PROM1-associated retinal dystrophy phenotypes, in the current study, we found that the morphological phenotype was associated with cone-rod dystrophy in all cases." (PMID 31199449, 2019). "The PROM1 gene, commonly associated with cone-rod dystrophies, may have dominant or recessive phenotypes that influence disease onset and severity." (PMID 31199449, 2019). "Meanwhile, we show for the first time that compound heterozygous mutations in PROM1 gene could cause cone-rod dystrophy." (PMID 24763286, 2014). "We showed that compound heterozygous mutations in PROM1 could cause cone-rod dystrophy for the first time." (PMID 24763286, 2014). "Mutations in human PROM1 were associated with arRP, macular degeneration, and cone-rod dystrophy." (PMID 20696082, 2010). "One such variant, PROM1 p.Arg373Cys, has been previously reported in many cases across the literature, on different haplotypic backgrounds and is known to cause a wide spectrum of disease, including bull's eye maculopathy, macular dystrophy, and cone-rod dystrophy." (PMID 35947379, 2022). "From a cohort of 8 patients with PROM1-related IRD, we identified 3 patients carrying the same variant (c.1354dupT) but expressing three different IRD phenotypes: Cone and rod dystrophy (CORD), Retinitis pigmentosa (RP), and Stargardt disease type 4 (STGD4)." (PMID 38956727, 2024). "Disease-causing variants of PROM1 have been linked to a wide range of retinal phenotypes, including macular dystrophy (MD), cone-rod dystrophy (CRD), and rod-cone dystrophy." (PMID 38072963, 2023). "USH2A was the most frequent gene associated with RP, RDH12 early-onset severe retinal dystrophy, ABCA4 Stargardt disease, PROM1 cone-rod dystrophy, and BEST1 macular dystrophy." (PMID 37217489, 2023).
cone-rod dystrophy (continued). "For STGD4, changes in PROM1 have been associated with variable phenotypes, which include cone rod dystrophy, macular dystrophy, retinitis pigmentosa, BEM, and the presence of flecks." (PMID 34440414, 2021). "Mutations in the PROM1 gene have also been reported in other MD diseases, such as STGD4 and cone-rod dystrophy, which demonstrates that mutations in same gene may manifest multiple clinical phenotypes." (PMID 29416601, 2018). "PROM1-related retinopathies can manifest as pan-retinal phenotypes, as in Retinitis Pigmentosa type 41 (RP type 41, OMIM 268000) and Cone-Rod Dystrophy (CORD, OMIM 604116 or 120,970); or as macular dystrophies such as Stargardt's disease type 4 (STGD4, OMIM 248200)." (PMID 38956727, 2024). "In addition, diseases with different inheritance patterns can result from one gene, e.g., the PROM1 gene, which leads to autosomal dominant STGD or autosomal recessive forms of RP, EORD, and cone or cone-rod dystrophy." (PMID 30374144, 2018). "We reviewed the literature and found mutations in PROM1 can lead to several diseases, including Stargardt disease (STGD4), retinitis pigmentosa (RP41), autosomal dominant cone-rod dystrophy (CORD12, CRD), macular dystrophy (MCDR2) and autosomal recessive cone-rod dystrophy (CRD)." (PMID 24763286, 2014).
diabetes (22 papers, 2011 to 2025). "This phenotype is to some extent amplified in the mouse model of drug-induced type 2 diabetes mellitus, where a delocalization of prominin-1 from ependymal ciliary structures results in ciliary tangling and sticking together, particularly at their tips." (PMID 39881297, 2025). "Further investigation revealed that PROM1, TFPI2, and PFKFB3 are crucial genes involved in the regulation of IL11 expression in patients with kidney stones and diabetes." (PMID 37480086, 2023). "The authors showed relatively low PROM1 expression by immunofluorescence in no DKD cases, with highest PROM1 expression in injured tubules in DKD cases,8 indicating increased cell turnover relative to no DKD controls (either with or without diabetes)." (PMID 40146907, 2025).
Stroke (22 papers, 2011 to 2024). Sudden impairment of blood flow to a part of the brain due to occlusion or rupture of an artery to the brain. "A clinical study shows that the level of circulating CD34/prominin-1(CD133)/VEGFR-2-triple positive vascular endothelial progenitor cells are significantly increased in stroke patients receiving NBP treatment compared with controls." (PMID 34631224, 2021). "Interestingly, we have found that, after stroke, aging not only decreases the number of astrocyte-like type B (in both sham and MCAO groups) but also of type-C cells (prominin-1+/EGFR+/nestin−/Mash1+ cells) in the SVZ, in this case, only after injury." (PMID 25958332, 2015).
triple-negative breast carcinoma (22 papers, 2013 to 2024). An invasive breast carcinoma which is negative for expression of estrogen receptor (ER), progesterone receptor (PR), and human epidermal growth factor receptor 2 (HER2). "PROM1 is linked to VEGF directly in this network and is attributed to poor prognosis in triple negative breast cancer due to its nuclear mislocalization." (PMID 30517191, 2018).
head and neck cancer (20 papers, 2011 to 2024). A primary or metastatic malignant neoplasm affecting the head and neck. "CD44, a hyaluronic acid (HA) receptor, and CD133, also known as prominin-1, have been considered potential CSC markers in head and neck cancer." (PMID 38966069, 2024).
squamous cell carcinoma (18 papers, 2008 to 2025). A carcinoma arising from squamous epithelial cells. "The PROM1 mutation was validated in 5 samples, including 3 adenocarcinomas (ADC) and 2 squamous carcinomas (SCC), with mutation rate of 1.4%." (PMID 24484648, 2014). "CSC-like cells were established from three squamous cell carcinomas (SCC) and three adenocarcinomas (AC) of the lung and were shown to express common CSC markers such as Prominin-1, CD44-antigen, and Nestin." (PMID 33925297, 2021).
adenoma (17 papers, 2011 to 2025). A neoplasm arising from the epithelium. "A number of studies proposed ISC as cells of origin for CRC since activating mutations of the Wnt/β-catenin pathway in LGR5+, Bm1+, or Prom1+ cells lead to adenoma development in mice." (PMID 33916891, 2021). "Up to date, several CSC-related markers have been described in adenomas, e.g., CD133, LGR5, PROM1, IL-8, OLFM4, and ASCL2, but more information is required to understand malignant transformation, despite current findings in the field." (PMID 36362041, 2022). "Average adenoma count was 23 in the small intestine and 10 in the large intestine of double mutant mice (Apc-/+Prom1-/-) compared to 17 and 10 in single mutant mice (Apc-/+Prom+/+), respectively." (PMID 25452936, 2014). "All sizes of adenomas increased in the double mutant mice (Apc-/+Prom1-/-), especially small adenomas (<2 mm in diameter)." (PMID 25452936, 2014). "The number of adenomas increased by 18% in Apc-/+Prom1-/- mice compared to those with Apc-/+Prom+/+." (PMID 25452936, 2014). "We now show that PROM1 can also be detected in early premalignant lesions in Apc-/+ mice under Wnt signaling regenerative pathways and that Prom1-/- deletion stimulates adenomas in Apc-/+ mice, which is a part of Wnt signaling regenerative pathways." (PMID 25452936, 2014). "In the Apc-/+ mice, that anti-PROM1 antibody showed intense staining in the majority of the epithelial cells within the adenomas." (PMID 25452936, 2014). "Quantification showed an expansion of PROM1 positive cells in the adenomas, P < 0.001." (PMID 25452936, 2014).
oral cancer (17 papers, 2009 to 2025). "Prominin-1 (CD133) and CD44 are stemness-related markers found in a variety of human tumors, including oral cancer, and the expression of these markers has been associated with the survival and prognosis of OSCC patients." (PMID 31878324, 2019). "CD133 (prominin-1) is presently considered a useful biomarker for prognosis and detection of cancer stem cell in a variety of human cancers, including oral cancer." (PMID 29285029, 2017).
prostate tumors (17 papers, 2009 to 2025). "Based on the degree of expression, we individually considered the following four tumor types for PROM1: esophageal, liver, pancreatic, and prostate tumors." (PMID 31164716, 2020).
Retinal dystrophy (17 papers, 2009 to 2026). Retinal dystrophy is an abnormality of the retina associated with a hereditary process. "We therefore suggest that the retinal dystrophy observed in the CORD7 family is entirely accounted for by the pathogenic variant identified in PROM1." (PMID 35947379, 2022). "Given the ubiquitous expression of PROM1, a remarkable feature of PROM1-associated retinal dystrophy in the current series was the absence of an extraocular phenotype." (PMID 31199449, 2019). "Furthermore, the gene editing strategy could contribute to the design of future gene therapy studies to treat early stages of PROM1-related retinal dystrophy." (PMID 38956727, 2024).